APOE (apolipoprotein E)
Diseases named in the same sentence as APOE in open-access papers (continued):
Sharing a sentence is not in itself a finding about the gene and the disease.
atherosclerosis (continued). "Early stages of atherosclerosis typically include altered homeostasis and activation of vascular endothelium, typified by loss of nitric oxide generation and increased expression of chemokines and adhesion molecules, which is evident in the apoE−/− model." (PMID 30538613, 2018). "In addition, NXT can inhibit the advanced atherosclerosis and enhance the plaque stability in apolipoprotein E deficient mice." (PMID 30140296, 2018). "Knockout of Cyp27A1 in apolipoprotein E-deficient mice revealed a gene dose effect with a 10-fold reduction in atherosclerosis severity observed in double knockout mice, and Cyp27A1 heterozygosity leads to accelerated atherosclerosis." (PMID 30283400, 2018). "This latter study suggested that atherogenic diets containing cholesterol might promote atherosclerosis in genetically predisposed humans due to quantitative limitations of different apoE gene polymorphisms." (PMID 30037080, 2018). "For instance, our present analysis demonstrated that the isoquinoline alkaloids and indole alkaloids could exert protective effects on atherosclerosis in apoE deficient mice." (PMID 29922166, 2018). "In this study, we used apolipoprotein E-deficient (ApoE−/−) mice to investigate if pu-erh tea drinking ameliorates atherosclerosis in early fatty streak formation and advanced fibrofatty plaque progression, focusing on anti-inflammatory effects and modulating macrophage apoptosis." (PMID 30210650, 2018). "In addition, ablation of the A-FABP gene in apolipoprotein E-deficient mice dramatically protects against atherosclerosis in the disease progress, and A-FABP exerts strong proatherosclerotic effects mainly through its actions on the macrophage." (PMID 29441065, 2018). "Global knockout of AIP1 in mice enhanced atherosclerosis process in an ApoE-deficient mouse model." (PMID 29731721, 2018). "We explored whether pu-erh tea consumption ameliorates atherosclerosis and the possible mechanism for its effects in apolipoprotein E-deficient (ApoE−/−) mice." (PMID 30210650, 2018). "It has been suggested that Cpn infection exacerbates atherosclerosis in conjunction with hyperlipidaemia; however, ApoE deficiency might influence the immune response to this pathogen and provides increased resistance to vascular infection." (PMID 29770337, 2018). "Furthermore, the adenovirus-mediated gene transfer of HO-1 reduced atherosclerosis in apoE-deficient mice." (PMID 30159103, 2018). "Therefore, apoE deficiency is associated with a decreased catabolism of atherogenic lipoproteins thus favoring hypercholesterolemia and atherosclerosis development." (PMID 30082772, 2018). "In ApoE‐deficient mice, pDCs were shown to aggravate atherosclerosis‐associated inflammation." (PMID 29364567, 2018). "In summary, our study shows that ICA could potently attenuate atherosclerosis and cause marked changes in gene and miRNA expression patterns in ApoE−/− mice." (PMID 30533443, 2018). "Moreover, the protective effect of the chemical chaperone 4-PBA against atherosclerosis in apolipoprotein E deficient (ApoE−/−) mice proved the implication of ER stress in atherosclerosis development." (PMID 29921793, 2018). "In spite of this, it is not clear whether Western diet feeding influences the gut microbiota in apoE KO mice or whether there are any associations between the altered gut microbiota profiling with atherosclerosis." (PMID 30021609, 2018). "Although the high-fat diet induced atherosclerosis quickly in ApoE-deficient mice, deletion of the ApoE gene may alter the results of the study." (PMID 30105261, 2018). "We generated the double knockout (DKO) mouse model of CD6 deficiency (CD6−/−) and apolipoprotein E deficiency (apoE−/−) on the DBA atherosclerosis-sensitive genetic background in order to determine if CD6 expression is atheroprotective due to increased production of natural IgM." (PMID 29615096, 2018).
atherosclerosis (continued). "Indeed, an increased EMMPRIN and CyPA expression is observed in atherosclerotic plaques in mice fed a high-fat diet, and double knockout mice deficient in apolipoprotein E (ApoE) and CyPA are protected against the development of atherosclerosis." (PMID 29419744, 2018). "However, if mice are genetically deficient in apolipoprotein E (apoE) such as apoE knock-out (KO) mice, they are sensitive to a Western diet and rapidly develop hyperlipidemia and atherosclerosis." (PMID 30021609, 2018). "Collectively, our study showed that there are marked changes in the gut microbiota of apoE KO mice, particularly challenged with a Western diet and these alterations may be possibly associated with atherosclerosis." (PMID 30021609, 2018). "In the apolipoprotein E–deficient mouse, the gut microbiota has an impact on the development of atherosclerosis, but whether such correlations are also present in rats requires investigation." (PMID 29615808, 2018). "The APOE ε4 allele also increases atherosclerosis risk and decreases lifespan." (PMID 30412599, 2018). "Therefore, it comes as no surprise that abnormal morphology and a substantial decrease in lung function are found in ApoE−/− mice which are susceptible to cardiovascular issues and are prone to atherosclerosis." (PMID 29364178, 2018). "Interestingly, in the double-knockout mice, we found that such animals developed comparable atherosclerosis as ApoE-deficient B6 mice." (PMID 30305306, 2018). "We think that the inflammatory action of C5a receptor may explain the observation of reduced atherosclerosis by C5a inhibition in ApoE deficient mice." (PMID 28323848, 2017). "However, in ApoE-deficient mice, apelin infusion inhibited atherogenesis and completely abrogated angiotensin II-accelerated atherosclerosis." (PMID 29070519, 2017). "To test a direct participation of TLR7 in atherosclerosis, we crossbred TLR7-deficient (Tlr7−/−) mice with apolipoprotein E-deficient (Apoe−/−) mice and produced Apoe−/−Tlr7−/− and Apoe−/−Tlr7+/+ littermates, followed by feeding them an atherogenic diet to produce atherosclerosis." (PMID 28405010, 2017). "HMGB-1 neutralization also reduces diet-induced atherosclerosis in apolipoprotein E-deficient mice." (PMID 28789654, 2017). "It has been recently shown that APOE-knockout rabbits, mimicking the symptoms of atherosclerosis in humans, have great susceptibility to type III hyperlipoproteinemia with remarkably elevated levels of cholesterol, triglyceride, remnant lipoproteins and massive aortic atherosclerosis." (PMID 29099857, 2017). "Genetic knockout of CCR2 (CCR2−/−) in the Apolipoprotein E-deficient (apoE−/−) mouse model of atherosclerosis resulted in a significant decrease in lesion size compared to apoE−/− controls, which was caused by a reduction in monocyte/macrophage recruitment to the atherosclerotic lesion." (PMID 28246398, 2017). "However, administration of DPP-4 inhibitors showed modest reduction or even no changes in blood pressure in patients with T2DM and in apolipoprotein E-deficient (ApoE−/−) mice which were susceptible to atherosclerosis." (PMID 28194113, 2017). "We set out to determine whether trehalose's autophagy-p62-mediated effects are mechanistically linked to the observed reduction in atherosclerosis by administering trehalose to mφATG5-KO and p62-KO mice (both on pro-atherogenic ApoE-null backgrounds)." (PMID 28589926, 2017). "However, studies on apolipoprotein E (ApoE-deficient mice) with deficient gene-targeting indicate that additional mechanisms of foam cell formation are also present in atherosclerosis." (PMID 28969682, 2017). "Further, deficiency of HDAC9 attenuates atherosclerosis in ApoE−/− mice." (PMID 29383092, 2017). "ApoE−/− mice with B cell-specific knockout of the gene encoding the helix-loop-helix factor Id3, known to have attenuated diet-induced atherosclerosis, have increased numbers of B-1b cells and increased IgM secreting cells in PVAT relative to littermate controls." (PMID 28970806, 2017).
atherosclerosis (continued). "Our study demonstrated favorable impact of the heparanase inhibitor PG545 on blood pressure, serum glucose levels, and oxidative stress in apolipoprotein E deficient mice, and as a result one can anticipate a favorable effect towards attenuating atherosclerosis progression by the inhibitor." (PMID 29226146, 2017). "Then, ApoE−/− mice were treated with a recombinant human IL-37 protein to investigate the association of IL-37 with innate and adaptive immunity in the development of atherosclerosis." (PMID 28607385, 2017). "Furthermore, atherogenic diet feeding to ApoE-/- CSE-/- mice exacerbated the development of atherosclerosis compared to mice with only ApoE or CSE deficiency." (PMID 29018349, 2017). "This conclusion is supported by previous studies, which demonstrated that inhibition of JNK pathway, but not the ERK pathway abolished oxLDL-induced foam cell formation and that inhibition of JNK activation attenuated low shear stress-induced atherosclerosis in ApoE-deficient mice." (PMID 29354064, 2017). "The present study analyzed the association of the APOE polymorphism with the incidence of cardiovascular events and death occurred in a short-term follow-up study of a cohort of 258 patients affected by advanced atherosclerosis." (PMID 28249002, 2017). "Moreover, in a prospective study of CVD risk in subjects with established atherosclerosis, the APOE content of APOA1-containing HDL particles was a much stronger predictor of future cardiac events than HDL-C or LDL-cholesterol levels." (PMID 26673204, 2016). "Moreover, VEGF promoted atherosclerosis progression in both apoE/apoB100 double-deficient mice and rabbits." (PMID 26908443, 2016). "Also, a direct relationship between apoE isoforms and premature atherosclerosis has been reported and recently apoE ε4 allele has been associated with the development of both T2DM and CAD." (PMID 26800892, 2016). "CD55 deficiency has also been shown to protect apoE−/− micefrom atherosclerosis." (PMID 27551317, 2016). "In contrast, ApoE‐deficient mice transgenic for LOX‐1 showed advanced atherosclerosis." (PMID 26493158, 2016). "Importantly, the compound has been found to regulate lipid metabolism and inhibit atherosclerosis in apolipoprotein E deficient (apoE-/-) mice." (PMID 27128486, 2016). "Nox4 deficiency results in resistance to flagellin-induced atherosclerosis in ApoE KO mice." (PMID 28018358, 2016). "For example, LPS administration aggravates atherosclerosis in apoE-deficient mice." (PMID 27167346, 2016). "The expression of P-selectin mRNA in the aortas of ApoE-deficient mice is strongly correlated with the progression of the lesions, suggesting that P-selectin is a good candidate for imaging and targeted therapeutic strategies in atherosclerosis." (PMID 27703301, 2016). "We also examined the effects of exposure to CNTs on the progression of atherosclerosis and analyzed their ex vivo role on the function of isolated EPCs of bone marrow origin in apolipoprotein E deficient (ApoE−/−) mice, a widely used model of human atherosclerosis." (PMID 27737702, 2016). "The authors compared the atherosclerotic lesions occurring in two different knockout (KO) animal models, apolipoprotein E (apoE)/eNOS-double knockout (DKO) and apoE-KO, demonstrating that a genetic deficiency of eNOS significantly increased atherosclerosis in the apoE-KO mouse model." (PMID 27651855, 2016). "ApoE−/− rats fed with standard chow at an age of 16 weeks develop impaired vascular compliance comparable to other ApoE-deficient animal models, yet at an atherosclerosis prone stage." (PMID 27277003, 2016). "Furthermore, in atherosclerosis models, such as the apolipoprotein (ApoE) deficient mouse, hypercholesterolemia is associated with Ly6C high monocytosis." (PMID 27146510, 2016). "Notably, another recent study in ApoE-deficient mice outlines a role for regulatory CD8+ T cells in limiting the development of aortic TLOs during atherosclerosis." (PMID 27752256, 2016).
atherosclerosis (continued). "To reveal the relationship between deregulated miRNAs and early-stage atherosclerosis, we used ApoE-deficient mice to build an animal model of atherosclerosis and analyzed the miRNA expression profiles of the atherosclerotic vascular wall using miRNA microarray analysis." (PMID 27918592, 2016). "Further studies are needed to verify our hypothesis that activation of AMPK/KLF4 signaling by loss of Elovl6 is protective against atherosclerosis by using double knockout mice of Elovl6 and apoE." (PMID 27881420, 2016). "Our findings show a significant positive association between autophagy and CysC expression in human carotid plaques, but an inverse correlation between autophagy and apoptosis in lesions in CysC‐deficient apoE−/− mice, proposing a new function for CysC as an autophagy regulator in atherosclerosis." (PMID 27079462, 2016). "The present study was conducted to determine whether lanatoside C affects the development of atherosclerosis in apolipoprotein E-deficient (ApoE–/–) mice." (PMID 26821916, 2016). "Further interpretation and discussion could be found at our research article entitled “Exogenous supplement of N-acetylneuraminic acid ameliorates atherosclerosis in apolipoprotein E-deficient mice”." (PMID 27419199, 2016). "To understand the mechanisms underlying atherosclerosis development and progression and how it impacts cell function, we use apolipoprotein E deficient (apoE−/−) mice, which show high levels of plasma cholesterol and develop atherosclerotic lesions that resemble human disease." (PMID 27229150, 2016). "Our study demonstrated that irisin significantly reduced atherosclerosis in apolipoprotein E-deficient mice via suppressing ox-LDL-induced cell inflammation and apoptosis, which might have a direct therapeutic effect on atherosclerotic diseases." (PMID 27355581, 2016). "In this pilot study, we aimed to investigate whether probiotics and pharmaceutical interventions could improve atherosclerosis in a gut microbiota associated manner in a well-established atherosclerotic animal model, ApoE−/− mice." (PMID 27821063, 2016). "In addition, chemical inhibition of Glo1 has been shown to induce atherosclerosis in ApoE deficient mice." (PMID 26788517, 2016). "Cadmium exposure was associated with atherosclerosis in the aorta in ApoE knockout mice." (PMID 26517380, 2016). "We herein show for the first time that the loss of ITCH results in a reduced development of atherosclerosis coupled with reduced hepatic fatty infiltration in the hypercholesterolemic ApoE−/− mouse model through reduced clearing of SREBP2 and SIRT6 respectively." (PMID 25777360, 2015). "The aim of this study is to investigate whether MsrA with PEP-1, a cell penetrating peptide, fused to its N-terminus can protect against oxidative stress in macrophages and can attenuate atherosclerosis in apolipoprotein E deficient (apoE−/−) mice." (PMID 26410585, 2015). "Additionally, administration of 1 μg IL-25 per day for 4 weeks in apoE deficient mice reduced atherosclerosis in the aorta both during initiation and progression of the disease." (PMID 25629516, 2015). "In this study we asked, whether administration of IL-25 to apoE deficient mice has any influence on atherosclerosis development." (PMID 25629516, 2015). "In contrast, the ApoE-deficient mice are a well-established model of atherosclerosis." (PMID 26076475, 2015). "Our results, on the apoE-/- model of atherosclerosis, agree with these previous reports and provide information on plaque size and composition in two highly susceptible areas for atherosclerosis, aortic arch and aortic root, in vivo." (PMID 26322890, 2015). "Recent evidence suggests that activation of AMPK in atherosclerosis has beneficial effects including reversing ER stress and stimulating reverse cholesterol transport from foam cells to reduce plaque area in mice deficient in apolipoprotein E (ApoE−/−)." (PMID 26196300, 2015).
atherosclerosis (continued). "TNF-α deficiency also reduced atherosclerosis in apolipoprotein E knockout mice." (PMID 25894557, 2015). "The overwhelming impact of hypercholesterolemia in apoE-deficient mice might make it difficult to accurately assess the glycemic effect on the development of atherosclerosis." (PMID 26313920, 2015). "Moreover, we and others have demonstrated that arsenic induces atheroma formation in apolipoprotein E-deficient (apoE-/-) mouse models of atherosclerosis." (PMID 26332580, 2015). "In addition, peptides isolated from a number of fish species have demonstrated antioxidant effects, and a salmon hydrolysate has been found to reduce plasma cytokine levels and atherosclerosis in apolipoprotein E-deficient (ApoE−/−) mice." (PMID 26193284, 2015). "Thus, we analyzed the anti-inflammatory and anti-thrombotic capacity of the fungal metabolite Galiellalactone in atherosclerosis-prone apolipoprotein E-deficient mice." (PMID 26076475, 2015). "The hypothesis that iNOS plays a causative role in the progression of atherosclerosis is supported by the observation that atherosclerotic lesions are diminished in iNOS/ApoE double-knockout mice relative to ApoE−/− mice." (PMID 26174316, 2015). "ApoE deficiency in mice (Apoe−/−) results in severe hypercholesterolemia and atherosclerosis." (PMID 26695075, 2015). "Likewise, miR-467b in macrophages protects apolipoprotein E-deficient mice from atherosclerosis, likely through decreasing both plasma and lesional CCL2 levels, and through suppression of lipoprotein lipase." (PMID 26001902, 2015). "Cav-1 deficiency is associated with reduced atherosclerosis in ApoE-KO mice." (PMID 25302702, 2014). "Moreover, the importance of T cells in atherogenesis has been highlighted by animal studies showing that transfer of CD4+ T cells aggravates, whilst CD4+ T cell deficiency attenuates atherosclerosis in apoE-/- mice." (PMID 25253303, 2014). "Studies in ApoE−/− mice genetically deficient for IL-17 or treated with anti-IL-17A antibodies demonstrated that absence or depletion of IL-17 attenuated development of atherosclerosis." (PMID 25352848, 2014). "However, a recent study showed that Cdkn2b deficient mice on an ApoE deficient background develop more atherosclerosis compared to ApoE deficient mice with an intact Cdkn2b gene." (PMID 24680834, 2014). "Moreover, they investigated the role of NKG2D in atherosclerosis using ApoE−/− mice genetically deficient for NKG2D or treated with anti-NKG2D antibodies." (PMID 25352848, 2014). "The purpose of the work was to study the impact of the endogenous nitric oxide synthase (NOS) inhibitor asymmetric dimethylarginine (ADMA) and its degrading enzyme, dimethylarginine dimethylaminohydrolase (DDAH1), on atherosclerosis in subtotally nephrectomized (SNX) ApoE-deficient mice." (PMID 24690995, 2014). "In this study we have analyzed whether a chronic increase in circulating hSAA derived from adipose tissue influences the development of atherosclerosis in ApoE-deficient mice." (PMID 24751653, 2014). "Moreover, modulation of CaSR expression on VSMCs in CKD by calcimimetic agents (R-568) was demonstrated to effectively delay progression of vascular calcification and atherosclerosis in uremic apolipoprotein E-deficient mice." (PMID 25134967, 2014). "Another important observation of this study is the fact that the degree of atherosclerosis in SNX treated ApoE-deficient mice of Group 3 is only marginally higher compared to our previously published data in age- and sex-matched ApoE-deficient mice without renal ablation." (PMID 24690995, 2014). "Despite the evidence for association between LPS, atherosclerosis progression, and M1 polarization, a study in germ-free apoE-deficient mice on low-fat chow diet showed increased atherosclerosis progression, suggesting that some bacteria in the gut flora have an anti-inflammatory effect." (PMID 25429291, 2014).